RUNX2 (RUNX family transcription factor 2)
Diseases named in the same sentence as RUNX2 in open-access papers (continued):
Sharing a sentence is not in itself a finding about the gene and the disease.
osteosarcoma (continued). "There is increasing evidence that abnormal expression of RUNX2 is a driving factor in osteosarcoma oncogenesis." (PMID 37663774, 2023). "In Osteosarcoma (OS) cells, miR-338-3p acts as a tumor suppressor by targeting runt-related transcription factor 2 (RUNX2) and CDK4, which inhibits the MAPK pathway." (PMID 36233210, 2022). "The role of Runt-related transcription factor 2 (Runx2) is also important in the metastatic process of many cancers, including osteosarcoma." (PMID 36714568, 2022). "Recent studies have shown that Runx2 in combination with osteopontin promotes the adhesion of osteosarcoma cells to the cell surface of the lung, an important step in the distant metastasis of osteosarcoma to the lung." (PMID 36714568, 2022). "We previously reported that the human osteosarcoma (OS) cell line 143b cannot undergo osteogenic differentiation due to Runx2 proteasomal degradation." (PMID 35635445, 2022). "In the skeleton system, RUNX2 is not only involved in the development, but also plays a crucial role in the formation and metastasis of osteosarcoma." (PMID 36429115, 2022). "The expression of CD4, OMD, and JUN was decreased in Osteosarcoma cells compared with osteoblasts, whereas RUNX2 and COL9A3 expression was increased." (PMID 36686663, 2022). "For example, miR-302b expression was significantly downregulated in osteosarcoma cell lines and clinical tumor tissues, and it can inhibit osteosarcoma cell migration and invasion by targeting runt-related transcription factor 2 (RUNX2)." (PMID 36339582, 2022). "As expected from the role of Runx2 in angiogenesis, RUNX2 is expressed at higher levels in cancers such as osteosarcoma, colon, prostate, and thyroid cancers as well as melanoma, suggesting its oncogenic role." (PMID 36231060, 2022). "lncRNA TUG1 promoted the development of osteosarcoma through runt-related transcription factor 2 (RUNX2)." (PMID 34039257, 2021). "For osteosarcoma cells, miR-338-3p inhibits RUNX2/CDK4 expression and the MAPK signaling pathway to inactivate tumor cells proliferation and metastasis." (PMID 34718336, 2021). "RUNX2 also induces cell-cycle arrest by the upregulation of p27 and suppresses cell proliferation in osteoblast lineages and osteosarcoma cells." (PMID 33801166, 2021). "Collectively, these results indicate that CBX4 is playing an important role in regulating Runx2 as well as cell migration and invasion in osteosarcoma cells." (PMID 32111827, 2020). "Osteosarcoma biopsies having high RUNX2 expression have been shown to have adverse tumor characteristics such as greater tumorigenicity, tumor progression, and metastases and have further been shown to regulate several cancer-related genes." (PMID 32695811, 2020). "Collectively, these results demonstrate that CBX4 promotes cell migration and invasion by enhancing Runx2 expression via recruiting GCN5 to the Runx2 promoter in osteosarcoma cells." (PMID 32111827, 2020). "The cell surface expression of cognate antigens was also upregulated or downregulated in Runx2 knockdown osteosarcoma cells." (PMID 32493499, 2020). "Present studies have identified that silenced SNHG20 inhibited the proliferation, invasion and induced apoptosis in osteosarcoma via miR-139/RUNX2 axis." (PMID 30846486, 2019). "It has recently been pointed out that RUNX2 overexpression is a key pathological factor in osteosarcoma, by controlling different cancer-related genes, which correlates with metastasis and insufficient chemotherapy response." (PMID 31236409, 2019). "On the other hand, it has been shown that miR-203 inhibits the migration and invasion of osteosarcoma cells by targeting RUNX2 mRNA." (PMID 30463392, 2018). "Intriguingly, runt-related transcription factor 2 (RUNX2) is expressed at higher level in numerous human cancers such as pancreatic cancer and osteosarcoma, indicating that, in addition to its pro-osteogenic role, RUNX2 has a pro-oncogenic potential." (PMID 29558908, 2018).
osteosarcoma (continued). "Considering that the aberrant overexpression of RUNX2 correlates to resistance to chemotherapy, it is indicative that miR-34c contributes to the improvement of chemo-sensitivity of drug-resistant osteosarcoma cells through the down-regulation of RUNX2." (PMID 29558908, 2018). "For example, RUNX2 gene is sometimes amplified, overexpressed in osteosarcomas and thus has been employed as a reliable marker for the estimation of their chemo-resistance." (PMID 29558908, 2018). "The mean expression level of Runx2 mRNA was lower in osteosarcoma tissue than in the adjacent normal bone tissues." (PMID 29042587, 2017). "Exogenous expression of Runx2 partially rescued the inhibitory effect of miR-302b on the invasion and migration activity of 143B osteosarcoma cells." (PMID 29042587, 2017). "RUNX2 is a master regulator of cell cycle-related factors in osteoblast progenitor cells and in osteosarcoma." (PMID 28977834, 2017). "The results showed that Runx2 mRNA expression levels in several osteosarcoma cell lines were significantly lower than those in the two osteoblastic cell lines." (PMID 29042587, 2017). "FGF/FGFR signaling increases the transcriptional activity of Runx2, an osteogenic transcription factor, which is overexpressed in several cancers including osteosarcoma." (PMID 28300755, 2017). "In the current study, preliminary evidence was presented about the negative regulatory role of miR-302b in osteosarcoma invasion and migration via targeting Runx2." (PMID 29042587, 2017). "While none of the antibodies were able to detect endogenous RUNX2 by Western blot, two were able to successfully immunoprecipitate RUNX2 from whole-cell lysates of U2OS osteosarcoma cells." (PMID 28542607, 2017). "This is consistent with the work of Del Mare and Aqeilan, which showed that WWOX-induced inhibition of invasion in osteosarcoma cells was mediated by RUNX2." (PMID 28977834, 2017). "The 6p21 region that contains the RUNX2 gene is amplified in some osteosarcomas, in consistent with a role of RUNX2 in osteosarcomagenesis." (PMID 26925584, 2016). "When YAP1 was knocked down by shRNA in MG-63 osteosarcoma cell line, proliferation and invasion were inhibited through inactivation of RUNX2 signaling." (PMID 27608849, 2016). "For instance, a high copy number gain of the RUNX2 locus has been reported in both human and dog osteosarcoma." (PMID 29056713, 2016). "Gene amplification and protein overexpression of the RUNX2 transcription factor, which is a regulator of bone renewal, has been proposed to drive osteosarcoma." (PMID 29056713, 2016). "Especially, Western blotting showed that freshly-isolated SSEA-4− cells expressed elevated levels of the osteogenic transcription factor RUNX2, which is indicative of osteoblastic commitment from MSCs or osteosarcoma TICs16." (PMID 25853231, 2015). "The U2OS osteosarcoma cells also demonstrate reduced motility following siRNA-mediated depletion of RUNX2." (PMID 26204939, 2015). "In support of this notion, amplification of chromosome 6p21, where RUNX2 exists, was detectable in a subset of osteosarcomas." (PMID 26512706, 2015). "Recently, we have found for the first time that depletion of RUNX2 in osteosarcoma-derived cells significantly enhances their adriamycin (ADR) sensitivity." (PMID 26512706, 2015).
osteosarcoma (continued). "An additional illustration of an indirect regulation of RUNX2 on the PI3K/AKT pathway comes from genomic promoter occupancy of RUNX2 in osteosarcoma cells." (PMID 26204939, 2015). "The Runt-related transcription factor, Runx2, is a key regulator of normal bone development, homeostasis and remodeling; however, Runx2 is also aberrantly expressed in several cancer types, including breast, prostate, lung, ovarian and osteosarcoma." (PMID 24479521, 2014). "The human osteosarcoma cell line SAOS-2 has persistently high RUNX2 protein levels, driven by the P2 promoter." (PMID 24835790, 2014). "Several reports indicate that in response to growth factor stimulation, phosphorylation and DNA binding activity of Runx2 is enhanced in osteogenic cell lines, endothelial cells and osteosarcoma cell lines." (PMID 24479521, 2014). "Runt-related transcription factor 2 (RUNX2) has been shown to play an important role in osteogenesis and development of osteosarcoma." (PMID 25266482, 2014). "In another report, gain-related overexpression of RUNX2 was observed in 60% of the analysed osteosarcoma tumours, and overexpression of RUNX2 is correlated with poor response to chemotherapy." (PMID 22685381, 2012). "The aberrations of RUNX2 were validated in five of the cell lines and five osteosarcoma tumour samples using quantitative real-time PCR and RT-PCR." (PMID 23144859, 2012). "RUNX2 was also shown to be recurrently gained and over-expressed in 12/29 osteosarcoma clinical samples based on identical types of microarray data." (PMID 23144859, 2012). "In recent years, an important role has emerged for the RUNX2 “platform protein” in osteosarcoma oncogenesis." (PMID 21197465, 2011). "In a study of 22 osteosarcomas by our lab, mRNA overexpression of RUNX2 was on average 3.3 times higher in tumours that had responded poorly (<90% necrosis) to neoadjuvant chemotherapy relative to tumours with good response (>90% necrosis)." (PMID 21197465, 2011). "In conclusion, the frequency of RUNX2 gain and elevated RUNX2 in osteosarcoma patient specimens as well as its documented functions lends to its possible value as a predictive factor and as a therapeutic target." (PMID 21197465, 2011). "The semidifferentiated state of osteoid producing osteosarcoma cells certainly raises questions about the Runx2-mediated juncture in osteoblast differentiation." (PMID 21403899, 2011). "Several recent studies of osteosarcoma specimens have reported constitutively high protein levels of RUNX2." (PMID 21197465, 2011). "While Runx2-driven osteoblast differentiation is clearly truncated in osteosarcoma, expression tends to be higher than in osteoblasts and correlates with a poor prognosis." (PMID 21403899, 2011). "Studies of osteosarcoma tumours have revealed that the RUNX2 DNA copy number together with RNA and protein levels are highly elevated in osteosarcoma tumors." (PMID 21197465, 2011). "Through activation by BMP/SMAD signaling, RUNX2 upregulates BAX expression to induce apoptosis in studies of the osteosarcoma cell line SAOS-2." (PMID 21197465, 2011). "Three more recently published studies were successful in linking RUNX2 expression with measures of clinical course in patients with osteosarcoma." (PMID 21197465, 2011). "RUNX2/RUNX2 thus has potential as a predictive biomarker for osteosarcoma, but a better understanding of the gene and protein in the context of the disease is necessary before considering targeted treatments and diagnostic, prognostic, and predictive tests." (PMID 21197465, 2011).
osteosarcoma (continued). "For the purpose of this paper, it will suffice to call attention to the chromosomal region 6p12-p21, which encompasses the RUNX2 gene and experiences recurrent gain and amplification in osteosarcoma." (PMID 21197465, 2011). "Our results also draw attention to the role of RUNX2 expression as a potential biomarker of chemotherapy failure in osteosarcoma." (PMID 20465837, 2010). "Because RUNX2 acts as cell growth suppressor in osteosarcoma cells, the elevated or ectopic expression of RUNX2 that is observed in a diverse range of tumor cells of either osseous or non-osseous origin is rather enigmatic." (PMID 21029421, 2010). "RUNX2 expression is inversely regulated with respect to cell growth in osteoblasts and deregulated in osteosarcoma cells." (PMID 21029421, 2010). "Moreover, studies have shown that miR-302b can suppress osteosarcoma cell migration and invasion by directly downregulating RUNX2 expression, further reinforcing the importance of this pathway in osteosarcoma pathogenesis." (PMID 40332124, 2025). "This new approach of considering RUNX2/HIF-1α as an integral transcription factor in osteosarcoma may aid in mitigating tumour development, improving treatment resistance, and accelerating the overall survival rate of patients with osteosarcoma." (PMID 40806771, 2025). "While no direct link to mineralization was found, β-catenin may still contribute via upstream effects on RUNX2, as described in other osteosarcoma models." (PMID 41258582, 2025). "Through this interaction, RUNX2 activity is modulated, leading to the downregulation of target genes involved in cell adhesion and motility, thereby suppressing metastatic behavior in osteosarcoma cell lines." (PMID 41141138, 2025). "Consequently, although the inverse correlation between WWOX and RUNX2 is well documented in osteosarcoma, direct evidence of a similar relationship in ES is currently under-characterized and remains to be firmly established." (PMID 41141138, 2025). "Moreover, the tumour suppressor MiR-203 reduced osteosarcoma cell growth and invasion and promoted apoptosis by enhancing chemosensitivity to cisplatin therapy by targeting RUNX2." (PMID 40806771, 2025). "The WWOX tumor suppressor gene is known to interact with RUNX2, a key osteoblast transcription factor, in osteosarcoma and bone biology; however, its expression and role along the WWOX-RUNX2 axis in ES tissue remains understudied, representing a gap in understanding ES molecular pathology." (PMID 41141138, 2025). "Modulation of NNMT-SIRT1 interactions, optimization of combination therapies, and targeted inhibition of RUNX2-driven signaling pathways could serve as valuable strategies to enhance treatment efficacy and overcome chemoresistance in osteosarcoma." (PMID 40332124, 2025). "This suggests that RUNX2 is a crucial factor in protecting osteosarcoma cells from apoptosis." (PMID 40806771, 2025). "The rationale for focusing on this axis lies in prior evidence showing that WWOX suppresses RUNX2 activity and thereby reduces metastatic potential in osteosarcoma, raising the possibility that a similar mechanism may exist in ES." (PMID 41141138, 2025). "Moreover, miR - 30a is significantly underexpressed in osteosarcoma cell lines, and it can target RUNX2, thereby inhibiting the proliferation, migration, and invasion of osteosarcoma cells." (PMID 40837012, 2025). "Furthermore, positive RUNX2 staining was found in 60% (12/20) of biopsy samples and 73% (8/11) of metastatic tumour samples from osteosarcoma patients." (PMID 40806771, 2025).
osteosarcoma (continued). "Moreover, the pathways involved in cell adhesion and motility are regulated by RUNX2, which leads to a more aggressive osteosarcoma phenotype." (PMID 40806771, 2025). "Therefore, this study emphasizes the significance of HIF-1α and RUNX2 in osteosarcoma and reinforces the need to regulate these two vital factors to establish an effective osteosarcoma treatment." (PMID 40806771, 2025). "Osteosarcoma often exhibits elevated levels of RUNX2 protein and mRNA16." (PMID 40806771, 2025). "Additionally, downregulation of β‐catenin simultaneously inhibits the expression of Runx2, a pro‐apoptotic gene highly expressed in osteosarcoma cells." (PMID 38800967, 2024). "Additionally, five key genes, including CD4, RUNX2, OMD, COL9A3, and JUN, were found to be associated with osteosarcoma progression." (PMID 39324133, 2024). "For example, nonreceptor tyrosine kinases (e.g., Src and Yes) can phosphorylate YAP and promote an interaction with the runt domain transcription factor 2 (Runx2), which subsequently targets a subnuclear location to suppress Runx2-mediated osteocalcin promoter activation in rat osteosarcoma cells." (PMID 38502585, 2024). "BRD4 can regulate RUNX2 expression directly in osteosarcoma." (PMID 38063851, 2024). "Furthermore, RUNX2 amplification in osteosarcoma has been confirmed through next-generation sequencing." (PMID 38659042, 2024). "RUNX2 expression may be correlated with the efficacy of therapy for osteosarcoma tumors; however, more patient studies are required to draw any firm conclusions." (PMID 37370857, 2023). "RUNX2 expression was measured by immunohistochemistry and analyzed for correlations with clinical data in 105 osteosarcoma patients, and it appeared to be an independent predictor of metastasis-free survival and overall survival in a multivariate survival analysis." (PMID 37108164, 2023). "RUNX2 is an important transcription factor for osteoblastic differentiation, and aberrant expression of the gene contributes to the development and progression of osteosarcoma." (PMID 37663774, 2023). "RUNX2 also has high expression in osteosarcoma and correlates with metastasis and poor survival." (PMID 37754840, 2023). "The regulatory link between miRNA-218 and RUNX2 was noted in osteosarcoma U2OS cell proliferation." (PMID 37108164, 2023). "In conclusion, RUNX2 offers promise as a prognostic factor and therapeutic target based on its well-established activities and its frequent increase in the tissues of patients with osteosarcoma." (PMID 37370857, 2023). "This suggests a correlation between FOXC1 and RUNX2 in osteosarcoma." (PMID 37754840, 2023). "Moreover, the silencing of ANAPC1 in human osteosarcoma (HOS) cells reduced RUNX2 expression, suggesting that ANAPC1 affects osteogenic differentiation through RUNX2." (PMID 37629076, 2023). "Studies have demonstrated that RUNX2 could alleviate high glucose‐suppressed osteogenic differentiation via the Wnt/β‐catenin pathway and it has also been discovered that RUNX2 could control osteosarcoma apoptosis via the Wnt/β‐catenin signaling pathway." (PMID 36200301, 2023). "The carcinogenic potential of RUNX2 overexpression and the possibility that its tumor suppressor functions are dysregulated suggest that the gain and amplification of chromosome 6p12-p21 plays a role in the etiology of osteosarcoma." (PMID 37370857, 2023). "Overexpression of RUNX2 hinders cell cycle entry in S phase and inhibits cell proliferation in pre‐osteoblasts, leading to abnormal osteogenic differentiation, which eventually progress to osteosarcoma." (PMID 36264762, 2022). "RUNX2 is highly expressed throughout the cell cycle in osteosarcoma cells." (PMID 36264762, 2022).